RN7SKP110 (RN7SK pseudogene 110)
Gene: Miscellaneous RNA gene on chromosome 6 (90,001,222 to 90,001,506, reverse strand). Ensembl gene ENSG00000222078.
Homologues: Orthologues: chimpanzee 7SK (99% identical), guinea pig 7SK (68% identical). Paralogues in human: RN7SKP180 (75% identical), RN7SKP45 (75% identical), RN7SKP37 (75% identical), RN7SKP79 (75% identical), 7SK (74% identical), RN7SKP255 (74% identical), RN7SKP95 (74% identical), RN7SKP217 (74% identical), RN7SKP176 (74% identical), RN7SKP102 (73% identical), RN7SKP130 (73% identical), RN7SKP20 (73% identical), and 283 more.